NR1D1 (nuclear receptor subfamily 1 group D member 1)
Diseases named in the same sentence as NR1D1 in open-access papers (continued):
Sharing a sentence is not in itself a finding about the gene and the disease.
anxiety disorder (2 papers, 2025). A category of psychiatric disorders which are characterized by anxious feelings or fear often accompanied by physical symptoms associated with anxiety. "Moreover, activation of NR1D1 by its agonist GSK effectively mitigated BPA-induced behavioral and molecular alterations, highlighting the therapeutic potential of targeting NR1D1 in anxiety disorders." (PMID 40559921, 2025).
autoimmune disease (2 papers, 2022 to 2025). A disorder resulting from loss of function or tissue destruction of an organ or multiple organs, arising from humoral or cellular immune responses of the individual to their own tissue constituents. "Also, NR1D1 regulates the development of Th17 cells and Th17 cell-mediated autoimmune diseases." (PMID 35911717, 2022).
Duchenne muscular dystrophy (2 papers, 2022 to 2024). Duchenne muscular dystrophy (DMD) is a neuromuscular disease characterized by rapidly progressive muscle weakness and wasting due to degeneration of skeletal, smooth and cardiac muscle. "Interestingly, myoblasts from patients with Duchenne muscular dystrophy displayed lower NR1D1 expression, whereas pharmacological NR1D1 activation ameliorated SR calcium homeostasis and improved muscle structure and function in dystrophic mdx/Utr+/– mice." (PMID 35917173, 2022).
fibrosis (2 papers, 2021 to 2023). the formation of excess fibrous connective tissue in an organ or tissue in a reparative or reactive process. "The diminished adipose fibrosis seen in Nr1d1Flox2-6:AdipoqCre mice may well reflect alteration in multiple processes, some of which may be under direct/indirect NR1D1 control." (PMID 34350828, 2021).
Hypercholesterolemia (2 papers, 2021 to 2025). An increased concentration of cholesterol in the blood. "The study of vulnerable plaque models in hypercholesterolemia ApoE (−/−) mice and NR1D1 (−/−) ApoE (−/−) mice revealed that NR1D1 deficiency could significantly increase the vulnerability/rupture of plaques." (PMID 40255337, 2025).
hyperlipidemia (2 papers, 2021 to 2024). "Moreover, overexpression of both NR1D1 and ApoA5 via AAV8 did not reverse severe hyperlipidemia and NASH in ApoA5-/- hamsters and fed an HFD (data not shown), raising a concern of gene therapy applied to patients with severe HTG due to ApoA5." (PMID 38505614, 2024).
invasive breast carcinoma (2 papers, 2016 to 2019). A carcinoma that infiltrates the breast parenchyma. "We used immunohistochemistry to analyze NR1D1 expression in primary invasive breast cancer specimens." (PMID 31779659, 2019). "Additionally, analysis of molecular profiling data sets of invasive breast carcinomas generated by the TCGA Research Network revealed an association between the ER stress markers and the HER2/neu, NR1D1 and PBP genes linked to lipogenesis in human breast tumors." (PMID 27464732, 2016).
liver fibrosis (2 papers, 2022 to 2023). "Another study showed that carbon tetrachloride (CCl4)-induced liver fibrosis in mice resulted in increased total liver m6A with specific increased m6A in NR1D1." (PMID 37628704, 2023).
multiple sclerosis (2 papers, 2023). A progressive autoimmune disorder affecting the central nervous system resulting in demyelination. "A GWAS study identified NR1D1 as a multiple sclerosis susceptibility gene." (PMID 38384322, 2023).
myopia (2 papers, 2023 to 2024). "The results revealed that NR1D1, PPP1R18, PGBD2, and PPP1R3D genes were associated with myopia, and these genes were potential biomarkers for myopia." (PMID 39597899, 2024). "Our study shows that NR1D1, PPP1R18, PGBD2, and PPP1R3D are effective as biomarkers in the diagnosis of myopia and that NR1D1, PPP1R18, PGBD2, and PPP1R3D may be potential therapeutic targets." (PMID 37740201, 2023). "The biomarkers selected by both algorithms were plotted in a Venn diagram, and a total of 4 genes (NR1D1, PPP1R18, PGBD2, PPP1R3D) were identified as biomarkers of myopia in the overlapping part." (PMID 37740201, 2023).
polycystic ovary syndrome (2 papers, 2023 to 2025). A disorder that manifests as multiple cysts on the ovaries. "Lactobacillus reuteri alleviated the liver gene expression of Nr1d1, the core circadian gene encoding REV-ERBα, in the circadian dysrhythmia-induced polycystic ovary syndrome (PCOS)." (PMID 38012609, 2023).
primary immunodeficiency (2 papers, 2023). "DPP4 and NR1D1 were associated with primary immunodeficiency, along with the T cell receptor signaling pathway." (PMID 37928394, 2023).
skin inflammation (2 papers, 2022 to 2023). "NR1D1 improves skin inflammation induced by Propionibacterium acnes by inhibiting Bmal1 transcription and the downstream NF-κB/NLRP3 axis, thereby preventing acne." (PMID 38072952, 2023).
triple-negative breast carcinoma (2 papers, 2019 to 2022). An invasive breast carcinoma which is negative for expression of estrogen receptor (ER), progesterone receptor (PR), and human epidermal growth factor receptor 2 (HER2). "For example, mice bearing triple negative breast cancer can impact the hepatic circadian gene expression causing alterations in several genes including the core clock genes Rev-Erba (Nr1d1), PER2, RORγ, and CLOCK26." (PMID 35046467, 2022).
abdominal aortic aneurysm (1 paper, 2025). Enlargement and ballooning of the vessel that supplies arterial blood to the abdomen, pelvis and legs. "NR1D1 (nuclear receptor subfamily 1 group D member 1) is the most highly upregulated nuclear receptor in abdominal aortic aneurysm (AAA) tissues." (PMID 40717128, 2025).
allergic asthma (1 paper, 2023). A asthma with a basis in a pathological type I hypersensitivity reaction. "Rev-erbα KO shows elevated Th2 cells and related cytokines indicating the protective role of NR1D1 in allergic asthma." (PMID 37664635, 2023). "Results from our study support the possible role of Nr1d1/2 (reduced mRNA expression) in chronic HDM-induced allergic asthma with heightened il4, il5, and il13 expression at ZT12." (PMID 37664635, 2023).
Arthritis (1 paper, 2020). Inflammation of a joint. "Activation of NR1D1 reduced the expression of proinflammatory cytokines in RA FLSs and macrophage activation in vitro and alleviated arthritis in vivo, suggesting NR1D1 to be a novel therapeutic target for inflammatory arthritis." (PMID 32071294, 2020).
Azoospermia (1 paper, 2022). Absence of any measurable level of sperm,whereby spermatozoa cannot be observed even after centrifugation of the semen pellet. "Further bioinformatics mining revealed that related clock genes (PER1, PER2, CRY2, NR1D1 and NPAS2) were down-regulated in non-obstructive azoospermia patients." (PMID 35910569, 2022).
bladder cancer (1 paper, 2024). "Cell viability, migration, and colony formation of bladder cancer cells were significantly inhibited after treatment with NR1D1 agonist SR9009." (PMID 39559540, 2024). "Thus, the overexpression of NR1D1 inhibited the tumorigenicity of bladder cancer cells, and NR1D1 played a role in cancer inhibition, implying it may be a new target for the treatment of bladder cancer." (PMID 39559540, 2024).
breast tumors (1 paper, 2016). "Statistically significant greater than twofold increases in expression in ER stress pathway genes are found to co-occur with increased levels of HER2/neu, NR1D1 and PBP in human breast tumors." (PMID 27464732, 2016).
COVID-19 (1 paper, 2023). A disease caused by infection with severe acute respiratory syndrome coronavirus 2. "In the present study, we identified six shared genes (SAMD9, PLEK, GZMB, JUNB, NR4A1, and NR1D1) of MG and COVID-19 patients through bioinformatic analysis." (PMID 38384322, 2023). "The differential expression analysis identified six differentially expressed genes (DEGs) shared by myasthenia gravis (MG) and COVID-19, namely SAMD9, PLEK, GZMB, JUNB, NR4A1, and NR1D1." (PMID 38384322, 2023).
glaucoma (1 paper, 2026). Increased pressure in the eyeball due to obstruction of the outflow of aqueous humor. "Glaucoma-induced phase shifts and amplitude alterations in the rhythmic expression of Per1, Per2, Nr1d1, and Bmal1 in the pituitary and adrenal gland, resulted in a temporal misalignment between the pituitary and adrenal rhythms." (PMID 42029480, 2026).
manic episodes (1 paper, 2015). "Moreover, it is found that lithium, a popular treatment for manic episodes, can inhibit glycogen synthase kinase 3β (GSK3β) and facilitate the degradation of NR1D1." (PMID 25789810, 2015).
methamphetamine dependence (1 paper, 2011). A drug dependence that is a psychological dependency on the regular use of methamphetamine. "To evaluate the association between NR1D1 and methamphetamine dependence, we conducted a case-control study of Japanese samples (215 methamphetamine dependence and 232 controls) with three tagging SNPs selected by HapMap database." (PMID 21886577, 2011). "These evidences indicate that rev-erb alpha gene (NR1D1) is a good candidate gene for the pathogenesis of methamphetamine dependence." (PMID 21886577, 2011). "We did not detect an association between NR1D1 and Japanese methamphetamine dependence patients in allele/genotype-wise analysis, or the haplotype analysis." (PMID 21886577, 2011). "Our findings suggest that NR1D1 does not play a major role in the pathophysiology of methamphetamine dependence in the Japanese population." (PMID 21886577, 2011).
mucopolysaccharidosis type 2 (1 paper, 2013). A lysosomal storage disease leading to a massive accumulation of glycosaminoglycans and a wide variety of symptoms including distinctive coarse facial features, short stature, cardio-respiratory involvement and skeletal abnormalities. "After 24 hours of treatment with idursulfase in fibroblasts of patients with Mucopolysaccharidosis type II the expression evaluated by NGS of the genes CLOCK, ARNTL2, NR1D1, NR1D2, and TIMELESS showed higher expression levels compared to untreated HS fibroblasts." (PMID 24083598, 2013).
muscular atrophy (1 paper, 2020). The loss of muscle tissue due to inactivity or disease. "Interestingly, 15-week old Nr1d1-/- mice showed progressive muscular atrophy while Nr1d1+/- mice retained a larger myofiber size than that of wildtype mice." (PMID 32407314, 2020). "Here we show that, unlike knockout mice, Nr1d1 heterozygous mice are not susceptible to muscular atrophy and in fact paradoxically possess larger myofiber diameters and improved neuromuscular function, compared to wildtype mice." (PMID 32407314, 2020).
non-small cell lung carcinoma (1 paper, 2023). A group of at least three distinct histological types of lung cancer, including non-small cell squamous cell carcinoma, adenocarcinoma, and large cell carcinoma. "To prove the tumor suppressive role of NR1D1 in vitro, we investigated whether NR1D1 overexpression (OE) induces cell cycle arrest or apoptosis in non-small cell lung cancer (NSCLC) cell lines (A549, H358, and H1299)." (PMID 37524704, 2023).
obstructive sleep apnea (1 paper, 2024). "Lastly, to further substantiate the regulatory role of the Nr1d1-Dusp1 axis, it would be essential to incorporate samples from patients suffering from obstructive sleep apnea complicated by pulmonary hypertension." (PMID 39472573, 2024).
osteosarcoma (1 paper, 2024). A usually aggressive malignant bone-forming mesenchymal neoplasm, predominantly affecting adolescents and young adults. "Therefore, this study aimed to identify the redundant and distinct roles of each isoform in controlling its target genes by comparing the transcriptome profiles of a panel of mutant U2OS human osteosarcoma cells in which either NR1D1 or NR1D2 was ablated." (PMID 38255844, 2024).
parasitemia (1 paper, 2022). "NR1D1, NDRG2, and PLD4 showed significant negative correlations with parasitemia, suggesting that downregulation of transcription could be driven by high parasite burden and/or the concomitant inflammation associated with symptomatic infection." (PMID 35475529, 2022).
psychosis (1 paper, 2011). "Therefore, we reasoned that NR1D1 may not play an important role in the pathophysiology of METH dependence and METH-induced psychosis in the Japanese population." (PMID 21886577, 2011).
pulmonary hypertension (1 paper, 2024). Increased pressure within the pulmonary circulation due to lung or heart disorder. "Mitochondrial dysfunction and fragmentation are recognized factors in pulmonary hypertension pathogenesis, and prior studies have linked Nr1d1 to their regulation." (PMID 39472573, 2024). "To invalidate Nr1d1 expression in an IH-induced rodents pulmonary hypertension model, we replicated pulmonary hypertension in rats through 6 weeks of IH exposure and in mice through 8 weeks of IH exposure." (PMID 39472573, 2024).
Right ventricular hypertrophy (1 paper, 2024). In this case the right ventricle is more muscular than normal, causing a characteristic boot-shaped (coeur-en-sabot) appearance as seen on anterior- posterior chest x-rays. "Similarly, in mice with CIH-induced PH, inhibition of Nr1d1 expression significantly alleviated CIH-induced remodeling and muscularization of peripheral pulmonary arteries, elevated RVSP, and right ventricular hypertrophy, thereby retarding the progression of CIH-induced PH in mice." (PMID 39472573, 2024).
septic shock (1 paper, 2021). Shock caused by infection; frequently caused by gram negative bacteria, although some cases have been caused by other bacteria, viruses, fungi, and protozoa; characterized by fever, chills, tachycardia, tachypnea, and hypotension. "While CRY1, NR1D1, NR1D2, DBP, PER2 were suppressed in septic shock patients, CRY2, surprisingly was significantly upregulated compared to healthy young men." (PMID 33900485, 2021). "In summary, the positive regulators of the transcriptional–translation feedback loop (CLOCK and ARNTL) were the least rhythmic, while negative regulators (NR1D1, NR1D2, CRY2) were the most rhythmic in septic shock patients." (PMID 33900485, 2021). "In addition, the expression of the clock genes CRY1, NR1D1, NR1D2, DBP, and PER2 were suppressed in septic shock patients, whereas CRY2 was significantly upregulated compared to healthy young men." (PMID 33900485, 2021).
Shock (1 paper, 2021). The state in which profound and widespread reduction of effective tissue perfusion leads first to reversible, and then if prolonged, to irreversible cellular injury. "Additionally, we found that NR1D1, NR1D2, CRY1, CRY2, PER1, PER2 and DBP had altered rhythms in at least some patients with septic shock." (PMID 33900485, 2021).
stomach adenocarcinoma (1 paper, 2023). "A study on stomach adenocarcinoma has revealed opposite results, where high NR1D1 and PER1 levels were correlated with poor OS." (PMID 37373286, 2023).
cancer (51 papers, 2009 to 2025). A tumor composed of atypical neoplastic, often pleomorphic cells that invade other tissues. "Nr1d1 is another candidate in Eaa11, and the co-activation of Erbb1, Grb7, and Nr1d1 has been linked to breast and other cancers." (PMID 35389339, 2022). "In addition, MCC950 treatment blocked the increased proliferation and EMT of cancer cells induced by CM from NR1D1-deficient macrophages in vitro." (PMID 37524704, 2023). "However, whereas NR1D2 is the major variant in various human cancer cells, NR1D1 is more abundant in normal tissues." (PMID 34440171, 2021). "In addition, the JAK/STAT3 signaling pathway, an intracellular signal transduction closely associated with cancer progression, was inhibited by NR1D1." (PMID 34330232, 2021). "In contrast, very few reports have analysed the role of NR1D1–2 in the different hallmarks of cancer." (PMID 40564218, 2025). "Together, NR1D1 is a high-function transcriptional suppressor that has therapeutic potential in cancer therapy." (PMID 39559540, 2024). "Before investigating the role of NR1D1 in cancer development, we analyzed the expression of NR1D1 mRNA in various cancer types from TCGA and GTEx databases using GEPIA2." (PMID 37524704, 2023). "In cancer types with a significant difference in NR1D1 expression between cancer and normal tissues, the correlation between the expression level of NR1D1 and survival rate was analyzed." (PMID 37524704, 2023). "As a result of analysis in 33 cancer types, NR1D1 mRNA levels were significantly lower in cancer tissues than in normal tissues in 10 cancer types, including LUAD." (PMID 37524704, 2023). "Numerous studies have investigated the role of circadian clock-related factors in the tumorigenesis of multiple cancer types, but little is known about the role of NR1D1 in cancer development." (PMID 37524704, 2023). "Further studies on the role of NR1D1 in other cancer types and factors correlated with the role of NR1D1 are needed to understand the role of NR1D1." (PMID 37524704, 2023). "Even if several studies have been conducted on the role of NR1D1 in cancer development, most of them are reports using synthetic agonists." (PMID 37524704, 2023). "NR1D1 was reported to be a tumor suppressor in OC, which retarded the growth of cancer cells by abrogating the JAK/STAT3 signaling pathway." (PMID 36003381, 2022). "This prediction corroborates observations made in the literature showing that two agonists of NR1D1 are lethal to cancer cells and oncogene-induced senescent cells, and calls for further investigation." (PMID 33975535, 2021). "Our data points to a role of circadian disruption in proliferation, apoptosis, and migration in CRC cells both in vitro and in vivo and highlights a function for the nuclear receptor, and core-clock element, NR1D1 as an enhancer of cancer invasiveness." (PMID 32244760, 2020). "The core-clock genes NR1D1, PER3, CSNK2A1, and the cancer associated gene VEGFA showed statistically significant results in our Cox-regression based survival plots (log rank test p ≤ 0.05)." (PMID 32295075, 2020). "Our results raise new questions concerning host–tumour interaction and show that core-clock genes are involved in key cancer properties, including the regulation of cell migration and invasion by NR1D1 in zebrafish xenografts." (PMID 32244760, 2020). "In recent years, various cancer targeting strategies related to NR1D1 have been introduced." (PMID 39559540, 2024). "Pharmacological activation of NR1D1 is lethal to many cancers." (PMID 34330232, 2021). "The intersection of differentially expressed genes (DEG) and our list of candidate genes, resulted in 12 elements including cancer associated genes (NRAS, MYC, and VEGFA), circadian drug targets (SOD2 and CES2) and core-clock and ECCN genes (AHR, CREB1, CSNK2A1, NFIL, NPAS2, NR1D1, and PER3)." (PMID 32295075, 2020). "Therefore, we examined whether NR1D1 regulates the macrophage-mediated proliferation of cancer cells." (PMID 37524704, 2023).